RNU6-392P (RNA, U6 small nuclear 392, pseudogene)
Synonyms: PBEF
Gene: Small nuclear RNA gene on chromosome 7 (106,208,167 to 106,208,267, forward strand). Ensembl gene ENSG00000201796.
Homologues: Orthologues: chimpanzee U6 (99% identical), dog U6 (86% identical), macaque U6 (83% identical), pig U6 (82% identical), rat LOC120100164 (78% identical), guinea pig U6 (77% identical), mouse Gm24116 (76% identical). Paralogues in human: RNU6-1124P (86% identical), RNU6-116P (86% identical), RNU6-1201P (86% identical), RNU6-12P (86% identical), RNU6-13P (86% identical), RNU6-24P (86% identical), RNU6-32P (86% identical), RNU6-338P (86% identical), RNU6-35P (86% identical), RNU6-633P (86% identical), RNU6-637P (86% identical), RNU6-737P (86% identical), and 1287 more.